ABL1 (ABL proto-oncogene 1, non-receptor tyrosine kinase)
Diseases named in the same sentence as ABL1 in open-access papers (continued):
Sharing a sentence is not in itself a finding about the gene and the disease.
cancer (continued). "Transient transfection of human PC3 cancer cells with the Abl1 3′UTR plasmid along with miR-4723 precursor led to a significant decrease in promoter activity when compared with the control vector suggesting that miR-4723 directly represses this gene." (PMID 24223753, 2013). "Aimed at the tyrosine kinase domain of the abnormal chimeric protein BCR/Abl1, imatinib was the first successful targeted cancer drug." (PMID 24376513, 2013). "The other important genes in this pathway like Abl1, Gml, Brca1, Zak, Xrcc5, Trex1, Pms1, Ccnu and Apex2 were also up regulated in the cancer cells." (PMID 22321936, 2012). "BCR::ABL1-targeting TKIs represent a typical success of precision medicine in cancer treatment." (PMID 40447744, 2025). "However, this discovery also raises several questions about the broader implications of ABL1’s activity at R-loops in other cancers." (PMID 40918650, 2025). "High expression or activation of ABL1 or FOXM1 overexpression are consistently observed in various cancers, but the possible links between them are largely unknown." (PMID 39060421, 2024). "Altogether, ABL1 expression level could be considered a prognostic factor in selected hematological malignancies and solid tumors." (PMID 36959186, 2023). "Since CREB1 functions in cancer signaling, together with data on the involvement of ABL1 and ERBB2 protein kinases in pathways in cancers, it suggests the presence of upstream cancer-associated tissue-specific transcriptional regulation in DLBC and THYM cancers." (PMID 37373333, 2023). "Interestingly, PTCH1 shows the highest mutation rate in 7% (127/1867; 7%) of cancers, followed by PDGFRA (89/1867; 5%), ABL1 (68/1867; 4%), FOSB (56/1,678, 3%), ALDH1A1 and CCND2 (48/1,678; 2.9%), (55/1867; 2.9%)." (PMID 36704357, 2022). "Overactivation of the ABL1 pathway leads to cancer development." (PMID 36466549, 2022). "Interestingly, overexpression of PTCH1, ABL1 and FOSB genes are reported to be associated with a low survival rate among cancer patients." (PMID 36704357, 2022). "Additionally, their fluorescence properties and the biological activity were investigated under normoxic vs. hypoxic conditions in an FGFR- or ABL1-driven cancer cell background." (PMID 34046181, 2021). "At present, ABL1 kinase is among the most common drug targets of approved therapeutic kinase inhibitors (ABL1 is the target of five molecular entities approved by FDA for cancer therapy)." (PMID 34361750, 2021). "Additionally, the selectivity test against other kinases also reveals a high affinity of R5 toward ABL1 and Tyro3 kinases, emphasizing its promising potential for the treatment of malignant tumors." (PMID 32117858, 2019). "Finally, we observe that the ABL1 cancer mutants display an increased cytosolic localization, which is associated with the oncogenic properties of the ABL1 kinase." (PMID 26758680, 2016). "ABL1 and ABL2 display mutations in approximately 1.5% and 4% of NSCLC cases, respectively, and ABL2 is amplified in approximately 8% of NSCLC cases (adapted from cBio Cancer Genomics Portal)." (PMID 26758680, 2016). "At the same time, targeted treatments have been developed which directly stop BCR::ABL1 from affecting cell growth and survival, replacing traditional, more toxic chemotherapy drugs which have a blanket effect on all developing cells, both healthy and cancer cells." (PMID 38550948, 2023).
cancer (continued). "Here, we performed a targeted sequencing panel of 324 cancer‐related genes (including ABL1, BCL2, CDH1, EGFR, etc.)at an average depth of 500× in all the specimens to identify mutations in genes that may be pivotal for synchronous primary cancer (BioProject accession number: PRJNA761143)." (PMID 36128740, 2022). "Further synthesis and in vitro tests of this compound against various cancer cell lines, where Axl, ABL1, and Tyro3 play a significant role in proliferation, division and metastases are further steps to be taken, and further indications for TAM inhibition may follow." (PMID 32117858, 2019). "The dataset included variables such as cancer diagnoses, patient demographics, BCR::ABL1 biomarker data, and detailed cancer treatment information, including pharmacy records." (PMID 41542066, 2026). "These proteins are involved in critical cancer-related pathways, including SRC in the MAPK signaling pathway, ABL1 in JAK/STAT signaling, PIK3CA in the PIK3-Akt pathway, and MAPK3 in the Ras signaling pathway." (PMID 40105884, 2025). "More recently, these inhibitors have demonstrated promising potential in non-cancer indications, owing to their multi-kinase activity and off-target inhibition of kinases such as PDGFR, c-KIT, FLT3, and native ABL1." (PMID 40732226, 2025). "Silphinene has demonstrated strong binding affinity to cancer-related proteins, including ERG, HER2, ABL1, and P13K-α, suggesting its potential as a molecular inhibitor in cancer therapy." (PMID 41455835, 2025). "The phosphorylation of SYCP2 by ABL1, which stabilizes R-loops and facilitates RAD51 recruitment, suggests that ABL1 acts as a critical mediator between transcription and DNA repair in cancer cells." (PMID 40918650, 2025). "Here, we engineered monobodies targeting the BCR::ABL1 tyrosine kinase for efficient delivery by the T3SS, quantified cytosolic delivery and target engagement in cancer cells and monitored inhibition of BCR::ABL1 signaling." (PMID 39415233, 2024). "We analyzed 8,805 3’ kinase gene fusions curated from the COSMIC, focusing on the seven most common kinase fusions involving ALK, RET, ROS1, NTRK1, NTRK3, ABL1, and BRAF genes found in various types of cancers." (PMID 38877018, 2024). "In Chronic Myeloid Leukemia (CML), the use of the 1st generation TKI imatinib to target the cancer driver, BCR::ABL1, results in 10 year survival rates of over 83%, approaching that of the healthy age-matched population." (PMID 37567965, 2023). "We investigated clinically relevant RTK fusion genes, namely ABL1, ALK, ERBB2, FGFR1-4, NTRK1-3, RET, and ROS1, because they are among the most frequent druggable cancer molecular biomarkers." (PMID 36009413, 2022). "We cannot discard a direct interaction among LINC00173 and BCR/ABL1 in BCP-ALL, since it is widely known that certain proteins involved in cancer favor tumor progression through modulation of lncRNA expression." (PMID 35719952, 2022). "According to the prediction and molecular docking results presented in this study, erianin shows high potential to interact with molecules like PIK3CA, RET, KIT, ABL1, and FLT3 in cancers, all of which were found to play important roles in cancer progression." (PMID 35372513, 2022). "Following treatment with nilotinib or genetic inhibition of ABL1/ABL2, cancer cells were sensitized to BRAF and MEK inhibitors and underwent cell death as well as decreased tumor growth." (PMID 34022881, 2021). "ABL1 is the most frequently rearranged kinase found in cancer cell lines, fused with different gene partners in 46 distinct cell lines, with the BCR-ABL1 fusion being the most frequent." (PMID 33257674, 2020).
cancer (continued). "Over the last decade, development of small molecule inhibitors of Abl1 and BCR-ABL, such as imatinib mesylate (imatinib, Gleevec), have dramatically reduced mortality rates in patients with CML and related cancers." (PMID 25822986, 2015). "MiR-196b-5p is dysregulated in many malignancies, has been related to cancer prognosis, and targets c-myc, ERG, MEIS1, FAS, ABL1, BCL-2 and several HOX genes." (PMID 25329796, 2014). "While most new approvals of drugs for target cancer therapies are directed against a few existing targets, such as EGFR, ABL1, only a small number of compounds are in development against novel targets." (PMID 22952662, 2012). "For the prostate dataset, our results show that three genes, namely MAF, ABL1 and SERPINB5, are cancer ones and most other top-ranked genes have a direct interaction with known cancer genes." (PMID 22830977, 2012). "This disruption of ABL1-mediated SYCP2 phosphorylation impairs the recruitment of RAD51 to R-loops, leading to defective HR and increased genomic instability, which ultimately sensitizes cancer cells to treatment." (PMID 40918650, 2025). "Cancers driven by a single acquired genetic alteration are rare and we did not identify concurrent genomic alterations required for clonal expansion beyond BCR::ABL1." (PMID 40205062, 2025). "Venetoclax has shown significant efficacy in both AML and ALL, while dasatinib (inhibiting BCR:: ABL1) and vinaclotide (inhibiting BCL-2) have a strong synergistic effect, which may effectively “starve” and “kill” cancer cells." (PMID 41366999, 2025). "In this study, we explored the potential role of ABL1 in TC-HR at R-loops, uncovering a novel and critical function of ABL1, which has not been extensively explored in the context of cancer biology." (PMID 40918650, 2025). "Nevertheless, our in vitro experiments robustly demonstrate that SYCP2 expression modulates sensitivity to ABL1 inhibition and is required for DNA repair via TC-HR, supporting a model in which ABL1 inhibitors preferentially target SYCP2-high, platinum-resistant cancer cells." (PMID 40918650, 2025). "By contrast, cancer incidences in Japanese survivors of the atomic bombs showed a peak in CML within 10 years of radiation exposure, raising the possibility that BCR::ABL1 driven clonal expansion and the trajectory to CML are unlike that of adult malignancies studied so far8." (PMID 40205062, 2025). "This indicates the potential for further functional work on other cancer genes in CML to direct future therapeutic targets independent of BCR::ABL1." (PMID 35158889, 2022). "CML is a rare hematopoietic stem cell disease wherein cells harbor the characteristic “Philadelphia chromosome” (Ph), resulting from a translocation between the BCR and ABL1 genes, forming the p210 or p190 isoforms of BCR-ABL1 tyrosine kinase which drive cancer cell proliferation." (PMID 35739111, 2022). "In the four cancer types, AKT and ABL1 were identified as potential drug targets." (PMID 33917859, 2021). "ABL1 was positively correlated with five TFs, suggesting that the FDA-approved anti-cancer therapeutic drug imatinib could be repurposed for high-EMT tumors with energy metabolic reprogramming in poor prognostic outcomes." (PMID 33917859, 2021). "In addition, circBA9.3 increases both ABL1 and BCR-ABL1 expression and reduces sensitivity of cancer cells to imatinib, suggesting that it is involved in CML resistance." (PMID 34747369, 2021). "Previous studies have confirmed that over 80% of ABL1 is expressed in MIBC through IHC experiments, and that imatinib, which inhibits the BCR-ABL1 gene from promoting tyrosine kinase action in cancer cell membranes, may be useful in these patients." (PMID 33952249, 2021).
cancer (continued). "For example, both ABL1 and BCL2 genes were validated as oncogenes, actionable genes, essential genes, genes in CGC, potential drug targets, and also contributed to hallmarks of cancer." (PMID 33240468, 2020). "Fusion rates differ across cancer types, and fusions may define some cancer types, such as BCR--ABL1 in chronic myeloid leukemia." (PMID 32471990, 2020). "To evaluate if IST5 affects kinase activity in cancer cells, we tested kinase inhibitory activity of IST5 in two custom-tailored panels including 54 relevant kinases, including Jak1, Jak2, Jak3, Tyk2, Abl1, Abl2, Lck, Fyn, Src and TrkB/C." (PMID 33217941, 2020). "Collectively, these findings indicate that the inhibitory effect of IST5 on Stat5 phosphorylation in cancer cells is not due to inhibition of Jak2 or other key kinases including Jak1, Jak3, Tyk2, Src, Lck, Fyn, TrkB/C, Abl1 or Abl2." (PMID 33217941, 2020). "Inhibitors with combined activity against c-Met and ABL1, such as HVS, could be a novel and logical target combination for treating a variety of human cancers." (PMID 27086914, 2016). "Although dual inhibition of c-Met and ABL1 sounds like attractive strategy for cancer therapy, there have not been known c-Met/ABL1 dual inhibitors, rendering HVS one of the novel dual TK inhibitors known to date." (PMID 27086914, 2016). "Cross-cancer alteration analysis for Abl-1, EGFR, Fyn, LCK, Src, ACK1 (TNK2) tyrosine kinases reveal that these genes are frequently altered in cancers, e.g. EGFR and TNK2 are recurrently amplified and mutually exclusive in a majority of the cancer cases." (PMID 26546517, 2015). "In fact, several anti-cancer drugs target MCSF1R (macrophage colony-stimulating factor 1 receptor), MSCGFR (mast/stem cell growth factor receptor), POTPKABL1 (proto-oncogene tyrosine-protein kinase ABL1) and VEGFR2 (vascular endothelial growth factor receptor 2), among others." (PMID 22768266, 2012). "In addition, six of the frequently hypermethylated genes, i.e., CCND1, COL4A2, HDAC2, AXIN2, ABL1 and GLI2, are included in the pathways in cancer map from the KEGG database." (PMID 22159500, 2012). "Conversely, we found no loss of ERBB2, EGFR, ABL1, RELA, and RELB transcript in c-MYC-destabilized cells compared to controls, and the 3′UTRMYC1-18-treated cancer cells tended to restore MYC expression towards the normal female mammary epithelial expression levels." (PMID 39123391, 2024). "Mutations in cancer-associated genes adversely affect outcome and their detection at diagnosis may guide therapeutic choice and offer non-BCR::ABL1 targeted therapies." (PMID 35932396, 2022). "Furthermore, some tumors overexpress specific cancer genes located on 1q (e.g., MDM4, ABL1, MCL1) indicating that these patients might benefit from targeted therapies in the future." (PMID 36230794, 2022). "The ABL1-I418T, PIK3CB-R231H, CHEK2:c.-4C > T, BRCA2-P3292L, ABL1-E459G, PRPF8-G1796R, PHF6-R274Q, WT1-R435X and ATM-C117Y variants were potentially important cancer variants which were not actionable." (PMID 35896598, 2022). "In addition, ErbB signaling pathway focused by us, the candidate gene ABL1 of AST, LDH and HBDH is enriched in this pathway, and the pathway plays a key role in the development of many cancers and the immune response, ABL1 also is also involved in the carcinogenesis and immune process." (PMID 36575369, 2022). "However, the observation that the many of the same genes are commonly found across multiple fusion pairs in cancers (e.g., BRAF, FGFR, ABL1, NTRK1/3) suggests that selection favours fusions that contain these genes when they arise due to the competitive advantages they confer on their host cells." (PMID 34573358, 2021). "Therefore, this influence on the expression of the TR region suppresses the expression of ABL1 in non-cancer cells, but does not suppress the expression of ABL1 in cancer cells." (PMID 33952249, 2021).
cancer (continued). "Interestingly, proteomics has played a lead role in mapping cancer signaling pathways and has successfully delineated the break point cluster region (BCR)-ABL1, extracellular signal-regulated kinase (ERK) pathways, and mechanistic target of rapamycin (mTOR) pathways." (PMID 29068423, 2017). "Additionally, in subsequent imatinib treatments, the cells often did not survive the replating, indicating ABL1 is required for the colony‐forming potential of the cancer cells." (PMID 26758680, 2016). "The elevated expression of ABL1 across several cancer types compared with noncancerous counterparts suggests that PROMPT-mediated transcriptional repression upon DSBs might be conducive in a variety of cancers." (PMID 38467418, 2024). "Therefore, expression of the respective target protein in the cancer cell is mandatory and genetic testing of cancer patients is compulsory, e.g., for HER2/neu overexpression for the use of trastuzumab, HER1 for the use of cetuximab or panitumumab or BCR/ABL1/c-kit for the use of imatinib." (PMID 35582146, 2019). "Across all cancer cell lines, we observed that many more genes were depleted rather than enriched in these screens, with DPH5, ZNF124, ABL1, and HNF4A showing the most significant toxicity." (PMID 39870664, 2025). "This dynamic, adaptive approach is not standardised in most other cancers save CML where dose and/or type of TKI therapy is adjusted based on results of sequential MRD-testing for BCR::ABL1." (PMID 38637690, 2024).